PPARG (peroxisome proliferator activated receptor gamma)
Diseases named in the same sentence as PPARG in open-access papers (continued):
Sharing a sentence is not in itself a finding about the gene and the disease.
breast cancer (continued). "Inhibition of PPARγ transcriptional activity using the antagonist GW9662 resulted in increased cell death, specifically of the ERBB2-positive BT474 and MDA-MB-361 breast cancer cells, in a time-dependent and dosage-dependent manner, but not of the ERBB2-negative MCF-7 or normal HMECs." (PMID 19298655, 2009). "Itis possible, however, that ICI may have directly repressed activation of PPARγ asICI was previously shown to inhibit the action of the selective PPARγagonist BRL 48, 482 in MDA-MB 231 breast cancer cell culture in the absence ofER." (PMID 18769493, 2008). "In summary, these observations suggest that reduced PPARγ expression does not contribute to the initiation of breast cancer; however, acceleration of PPARγ signaling after tumor initiation markedly promotes breast cancer development." (PMID 19061500, 2008). "An additional level of crosstalkis constituted by the fact that PPARγ cofactors, such as steroid receptor coactivator (SRC) family members(e.g., AIB/SRC3 in breast cancer), are phosphorylated by MAPKs and thereby arealtered in their ability to coactivate transcription." (PMID 18596912, 2008). "PPARγ also modifies ER signaling by promoting itsubiquitination and degradation as well as by upregulating CYP19A1 (aromatase) activity, which can blunt the activity of aromatase inhibitors usedto treat patients with ER+ breast cancer." (PMID 18566686, 2008). "Therefore, PPARγ is an important mediator of cell growthinduced by sulindac.Similarly, β-carotene was shown to induce apoptosisand increase PPARγ expression at both mRNA and proteinlevels in MCF-7 breast cancer cells." (PMID 18615184, 2008). "RZG has been shown for instance to reduce the expression/activity of MMPs in a PPARγ-independent manner in adrenal and pancreatic tumour cells and to increase the expression of TIMP-1 in breast cancer cells." (PMID 16969347, 2006). "This synergistic effect has also been found in liposarcoma and breast cancer cell lines but not in the present study, in spite of the constitutive expression of PPARγ and RXRα in the nuclei of HCC cells." (PMID 15467764, 2004). "In the present study with the human breast cancer cell line MCF-7, we have compared the effects and interactions of both native and synthetic retinoids (ATRA and 4HPR) and PPARγ agonists (15-deoxy-delta 12,14-prostaglandin J2, 15d-PGJ2 and TGZ) on cell growth, survival and ceramide production." (PMID 15505623, 2004). "In addition, PPARγ activation promotes the expression of its target gene PTEN to inhibit the PI3K/AKT/mTOR signaling, thereby suppressing the proliferation of breast cancer cells and the tumorigenicity and metastasis of cervical, glioblastoma, and liver cancer stem cells." (PMID 41481427, 2026). "Similarly, the highly metastatic breast cancer cell line MDA-MB-231 exhibits lower PPARγ expression compared to the non-metastatic MCF-7 cells." (PMID 41373547, 2025). "PGZ-activated PPARγ targets estrogen receptors (ER) and aromatase, activates the tumor suppressor gene PTEN to inhibit ER expression or induce proteasome-dependent ER degradation, and inhibits aromatase through PGE2 and BRCA1 signaling pathways to prevent breast cancer progression." (PMID 37251321, 2023). "By inhibiting NF-κB, activated PPARγ significantly reduced the expression of pro-inflammatory, pro-angiogenic, and pro-transfer signaling molecules in the TME, including IL-6, IL-8, CXCR4, MMP2, and MMP9, which further inhibited the activity of tumor cells in breast cancer." (PMID 37251321, 2023). "In addition to its ligand-activated state, PPARγ also involves itself in the development of breast cancer in a non-ligand-independent manner." (PMID 36611922, 2022). "Furthermore, in several breast cancer cell lines, RGZ activated the human Fas ligand (FasL) promoter in a PPARγ-dependent manner, increased the binding of PPARγ with Sp1 to the Sp1 sequence located within the FasL promoter, and positively regulated FasL expression." (PMID 36611922, 2022).
breast cancer (continued). "Furthermore, the low expression levels of ADIPOQ (HR = 0.416, p < 0.01), IGF1 (HR = 0.458, p < 0.05), LEP (HR = 0.527, p < 0.05), NR3C1 (HR = 0.457, p < 0.05), and PPARG (HR = 0.491, p < 0.05) were notably related to the poorer BCSS of breast cancer patients with tumor pathological stages III–IV." (PMID 35317079, 2022). "Akt isoform specificity has yet to be extensively studied in breast cancer in relation to FASN, although prostate cancer studies have revealed a relationship between Akt3 and FASN involving the two as downstream effectors of peroxisome proliferator-activated receptor gamma (PPARG) activation." (PMID 34298660, 2021). "Furthermore, we observed no response in BC ADSCs to the PPARγ inhibitor T0070907, showing an impaired activation of this receptor in adipose cells surrounding the breast cancer microenvironment." (PMID 31511776, 2019). "PPARγ, the most important upstream regulator, was predicted to be activated: this result suggests that PPARγ could be explored as potential therapeutic target for HR+HER2− breast cancer." (PMID 30305115, 2018). "Although data from human trials suggest the efficacy of TZDs as monotherapy in prostate cancer and glioma and as chemopreventive agents in colon, lung, and breast cancer, the action of TZDs are highly complex and those actions do not correlate with cellular PPARγ expression status and/or activation." (PMID 29163813, 2017). "We found that ligand-activated PPARγ downregulated CXCR4 transcriptional activity through the recruitment of the silencing mediator of retinoid and thyroid hormone receptor (SMRT) corepressor onto a newly identified PPAR response element (PPRE) within the CXCR4 promoter in breast cancer cell lines." (PMID 27556298, 2016). "Among the synthetic compounds that selectively activate PPARγ, the thiazolidinediones (TDZ), the most potent insulin-sensitizing drugs available in clinical settings, have been shown to inhibit cell proliferation and induce apoptosis in different in vitro and in vivo models of breast cancers." (PMID 27556298, 2016). "Moreover, we observed, as expected, that ligand-activated PPARγ reduced breast cancer cell migration induced by SDF-1α (data not shown)." (PMID 27556298, 2016). "Finally, we have demonstrated the inhibitory effects of activated PPARγ on CXCR4 expression and migratory abilities also in CAFs as an additional mechanism that may impact breast cancer progression." (PMID 27556298, 2016). "Intriguingly, DMBA + ROSI-treated PPARγ-MG KO mammary tumours exhibited a significant ~4-fold increase in Cox-2 compared to DMBA Only-treated PPARγ-MG KOs (p < 0.01), as well as a significant ~3-fold increase in Cox-2 compared to DMBA + ROSI-treated PPARγ-WT mice (p < 0.01)." (PMID 25889730, 2015). "These surprising outcomes may be explained, at least in part, by the increased total mammary tumour and malignant mammary tumour incidences, and decreased mammary tumour latency, that were observed in DMBA + ROSI-treated PPARγ-MG KOs compared to those treated with DMBA alone." (PMID 25889730, 2015). "However, some reports previously argued that PPARγ activation is non-tumor suppressive in prostate cancer, and even promotes tumorigenesis in breast cancer." (PMID 26244663, 2015). "Our results showed that PTER-ITC activated PPARγ expression in a dose-dependent manner, followed by downregulation of its anti-apoptotic genes (Bcl-2 and survivin) to induce noteworthy levels of apoptosis in hormone-dependent (MCF-7) and -independent (MDA-MB-231) breast cancer cells." (PMID 25119466, 2014). "The exact role of PPARγ in breast cancer cell proliferation and survival is not clearly understood." (PMID 23431460, 2013).
breast cancer (continued). "The role of PPARγ in modulating telomerase activity in breast cancer cells has not been studied and may have therapeutic potential." (PMID 20650001, 2010). "Theseinitial studies concretely demonstrated that PPARγ acts as a tumor suppressor in a cancer settingby upregulating PTEN transcription.However, these studies were performed solely in breast cancer cell lines,leaving the speculation that these observations are cancer-type dependent." (PMID 19096712, 2008). "However, the controversial nature of current studies and disappointing results from clinical trials raise questions about the contribution of PPARγ signaling in breast cancer development in the absence of stimulation by exogenous ligands." (PMID 19061500, 2008). "We could show very recently that cytoplasmic PPARγ is a negative prognosticator in breast cancer." (PMID 36230483, 2022). "Interestingly, ligand-activated PPARγ was shown to attenuate M1 and M2 polarization of breast TAMs, representing good tools to maintain macrophages in an inactive state that does not affect breast cancer progression." (PMID 33352766, 2020). "However, whether cytoplasmic PPARγ might be important for predicting human breast cancer development and progression was not elucidated." (PMID 23939428, 2013). "Interestingly, GW9662 enhanced the inhibitory effect of the agonist rosiglitazone on breast cancer cells rather than rescuing tumor growth, suggesting that PPARγ activation may not be involved in inhibition of survival and cell growth caused by agonists." (PMID 22693486, 2012). "The mRNA levels of FABP4, ADIPOQ, PPARG, CD36, and PPARGC1A were significantly lower in patients with breast cancer than in those without breast cancer." (PMID 36114448, 2022). "In contrast to breast carcinoma cells, pan-HDAC blockade with LBH589 did not upregulate PPARγ expression or augment its activity in untransformed human breast epithelial cell lines MCF10A and MCF12A." (PMID 34580286, 2021). "Some researchers identified a protective role of PPARγ against palmitate-induced lipotoxicity in ERBB2-positive breast cancer cell lines (BT474 and MDA-MB-361), but not in other types of breast cancer (MCF-7) and normal cells." (PMID 29966227, 2018). "The present study demonstrated BRCA1mut breast cancer cases to overexpress VDR, RXR and PPARγ - especially in the absence of ‘classical’ hormone receptors." (PMID 28427429, 2017). "Thus, lipogenic enzyme inhibitors, modulators of PPARγ transcriptional activity, and, perhaps, dietary omega-3 polyunsaturated FAs (e.g., DHA) may provide novel therapeutic strategies for the clinical management of HER2-positive breast carcinomas and may increase the efficacy of standard therapies." (PMID 26640797, 2015). "While the PPARγ agonist 15d-PGJ2 increases transcriptional activity and CD36, the antagonist GW9662 reduces this but does not block agonist-induced apoptosis in breast cancer cells." (PMID 18947424, 2008). "The mRNA expression levels of FABP4, ADIPOQ, PPARG, CD36, and PPARGC1A were significantly lower in patients with breast cancer, whereas the mRNA levels of CREBBP were not different between patients with breast cancer and normal breast tissues." (PMID 36114448, 2022). "Increasing evidence has indicated that PPARγ is non-activated in TNBC cells and its activation might inhibit the metastasis of breast cancer cells." (PMID 29316690, 2018). "Taken together, these data suggest PPARγ is required for normal PTEN expression in malignant mammary tumours, but PTEN is not an early PPARγ downstream signaling target in benign mammary tumours, and may be a fruitful area for research in future studies." (PMID 25889730, 2015). "Our group has previously shown that overexpression of PPARγ can down-regulate Skp2 expression in MDA-MB-231 breast tumor cells, but whether or not Skp2 influences PPARγ function in breast cancer has not yet been determined." (PMID 23939428, 2013).
atherosclerosis (368 papers, 2006 to 2026). A disease characterized by the build-up of fatty material and calcium deposition in the arterial wall resulting in partial or complete occlusion of the arterial lumen. "By reducing oxidative stress through nuclear factor erythroid 2-related factor 2 (Nrf2) pathway activation, PPARγ helps preserve endothelial function, reducing the risk of atherosclerosis and CVDs." (PMID 40926269, 2025). "Loss of PPARγ function in the vascular endothelium enhances atherosclerosis in high-fat diet-fed apoE-/- mice." (PMID 40440080, 2025). "With respect to the FunRich FEA results for TF GOs of the TAFI interactors and associated miRNAs, only PPARG was recently reported to play contradictory roles in the pathophysiology of thrombosis and atherosclerosis." (PMID 37759718, 2023). "Peroxisome proliferator-activated receptor gamma (PPARγ), a nuclear receptor of the steroid superfamily, is a potent target for counteracting risk factors of atherosclerosis." (PMID 37833942, 2023). "PPARG is associated with the regulation of processes related to inflammation, cell differentiation, metabolism, atherosclerosis, and proliferation, which are closely associated with the development of CVD." (PMID 35757636, 2022). "For example, in atherosclerosis, PPARγ promotes the expression of CD36, causing enhanced uptake of lipids by macrophages; it also accelerates cholesterol efflux by upregulating the expression of ABCA1 and ABCG1." (PMID 35432274, 2022). "PPARγ is associated with the pathology of many diseases, such as obesity, atherosclerosis, diabetes, and cancer." (PMID 36359869, 2022). "Regarding the role of the PPARγ polymorphism rs3856806 at the onset of atherosclerosis, the results are contradictory." (PMID 35203258, 2022). "Homocysteine-mediated DNA methylation of PPARα and PPARγ participates in the pathogenic mechanism of atherosclerosis." (PMID 34362460, 2021). "The downregulation of PPARγ expression has been associated with atherosclerosis, hypertension, and vascular calcification." (PMID 33158204, 2020). "Ligands of PPARγ decrease cytokines such as nitric oxide synthase, IL-6, and tumor necrosis factor α thereby reducing the inflammatory response associated with atherosclerosis." (PMID 28243251, 2017). "Specifically, PPARG has been implicated in the regulation of processes concerning metabolism, inflammation, atherosclerosis, cell differentiation, and proliferation." (PMID 27579030, 2016). "Currently available data indicate that PPARγ agonists improve atherosclerosis by ameliorating systemic metabolic risk factors for atherogenesis and inflammatory events." (PMID 21269478, 2011). "In contrast, three studies showed less intima-media carotid thickening in carriers of the PPARG Ala12 allele suggesting a possible relation between this variant and sub-clinical atherosclerosis." (PMID 20016803, 2009). "Thiazolidinediones (TZDs) are PPARγ agonists that improve insulin sensitivity, reduce triglyceride levels and decrease the risk of atherosclerosis in diabetic patients." (PMID 18302760, 2008). "However, Ascophyllum nodosum-derived fucoidan is found to inhibit the expression of PPARγ and elevate the expression of PPARα, thereby attenuating hyperlipidemia and atherosclerosis in ApoE-deficient mice." (PMID 38699583, 2024). "Given the favorable anti-inflammatory and antiatherogenic effects of PPARγ activation in atherosclerosis, PPARγ agonists might lower the risk of cardiovascular disease." (PMID 36768666, 2023). "Furthermore, PPARγ activation has been linked to improvementsin endothelial function and a reduction in atherosclerosis, contributing to better cardiovascular health." (PMID 37901293, 2023). "A recent study showed that the higher contents of polyunsaturated fatty acids in monocytes stimulated by Pam3Cys (TLR ligand) can activate peroxisome proliferator-activated receptor-gamma (PPAR-γ), which is closely associated with the establishment of innate immune memory during atherosclerosis." (PMID 36552836, 2022).
atherosclerosis (continued). "In addition, PPARγ deficiency in PVAT enhances atherosclerosis and results in vascular and systemic inflammation." (PMID 33391033, 2020). "Recent evidence suggested that dietary quercetin may be effective in lowering the risk of atherosclerosis by upregulating PPARγ, LXR-α, and ABCA1 and downregulating CD36 in the liver of apoE-/- mice fed HFD." (PMID 33261070, 2020). "PPARγ agonists can alleviate atherosclerosis by improving metabolic risk factors known to cause atherosclerosis and to reduce inflammatory factors in the arterial wall with an improvement in endothelial function seen in diabetic and hypercholesterolemic animals." (PMID 32190383, 2020). "Weight loss increases Pparα and Pparγ, associated with a decrease in atherosclerosis." (PMID 23620818, 2013). "Moreover, PPARγ influences fatty acid storage in the adiposetissue and is implicated in insulin resistance and atherosclerosis." (PMID 18551186, 2008). "In conclusion, PFOS and PFOA induced lipid accumulation associated with increased PPARγ and Nrf2 activity, including changes in the expression of enzymes and markers of inflammation and oxidative stress, which are critically involved in the development of atherosclerosis and CVD." (PMID 40728694, 2025). "Therefore, quercetin, by increasing or activating PPARγ and associated signaling cascades in the heart, exerts cardioprotective effects in CVDs, including hypertension, heart failure, ischemia, and atherosclerosis due to antioxidant, anti-inflammatory, and antiapoptotic disease." (PMID 36092543, 2022). "Furthermore, TNF-α regulation of PPARγ activity has been linked to the etiology of atherosclerosis." (PMID 35656103, 2022). "Previous studies have shown that PPARγ is highly expressed in macrophage foam cells from atherosclerotic lesions and has been demonstrated in cultured macrophages to both positively and negatively regulate genes implicated in the development of atherosclerosis." (PMID 18485218, 2008). "The relatively modest effects of PPARγ deficiencies in fat,muscle, and liver provided the impetus for broadening the analysisof Pparg KO to additional cell types that participate inobesity-associated metabolic complications, namely diabetes,hypertension, and atherosclerosis." (PMID 17389768, 2007). "Previous studies have established that CD36 influences PPARγ activity, which in turn affects various physiological processes, including atherosclerosis, liver cholesterol biosynthesis, and adipose mitochondrial biogenesis." (PMID 41267927, 2025). "Inflammatory macrophages can be polarized toward the M2 phenotype to eliminate atherosclerosis by increasing the expression of PPARγ, and preventing PPARγ activation significantly impairs macrophage phagocytosis." (PMID 39737788, 2025). "The PPARγ/LXRα signaling pathway plays a critical role in atherosclerosis pathogenesis by modulating macrophage cholesterol efflux and inflammatory responses." (PMID 40872505, 2025). "PPARγ exerts anti-atherosclerosis effects by promoting the removal of cholesterol from macrophages via cholesterol transporters such as ABCA1 protein." (PMID 41464973, 2025). "UCP1 is activated by PPARα and PPARγ has been shown to inhibit atherosclerosis by reducing vascular inflammation." (PMID 40753563, 2025). "Previous studies have identified several miRNA-regulatory axes involved in PPARG regulation in atherosclerosis models (e.g., miRNA-130a/PPARG/NF-κB and miRNA-19b/PPARG/NF-κB)." (PMID 41009355, 2025). "HOXA5 safeguards against atherosclerosis via peroxisome proliferator-activated receptor gamma (PPARγ), whereas HOXB9 exacerbates inflammation through bone morphogenetic protein 4-tumor necrosis factor (BMP4-TNF)." (PMID 41181801, 2025).